ANGPTL8 (angiopoietin like 8)
Diseases named in the same sentence as ANGPTL8 in open-access papers (continued):
Sharing a sentence is not in itself a finding about the gene and the disease.
metabolic syndrome (continued). "In particular, we found that circulating human ANGPTL8 levels were positively correlated with obesity and dyslipidemia, as estimated by increased TG and LDL-cholesterol levels and decreased HDL-cholesterol levels, suggesting that circulating ANGPTL8 concentrations predict future CVD development." (PMID 29538435, 2018). "Finally, increased ANGPTL8 levels were observed in obesity, impaired glycometabolism and dyslipidemia." (PMID 29538435, 2018). "However, many epidemiological studies have demonstrated the alteration of ANGPTL8 concentration in metabolic diseases including diabetes, obesity, and metabolic syndrome." (PMID 29719529, 2018). "Our data shows positive correlation between ANGPTL8 and HsCRP suggesting that the inflammatory process might be connected to the increase in ANGPTL8 in humans that could result in aggravated dyslipidemia." (PMID 26850725, 2016). "Furthermore, as ANGPTL8 functions as a switch, inhibiting it may be able to reverse thrifty traits including hypertriglyceridemia, metabolic syndrome, obesity, and CVD." (PMID 39274442, 2024). "Constant feeding increases circulation ANGPTL8 levels, leading to increased adipose storage (fat) and hypertriglyceridemia, and it is not a huge stretch to reckon that the same ANGPTL8 protein that likely safeguarded our ancestors from famine now predisposes humans to metabolic syndrome." (PMID 38303975, 2023). "However, due to the lack of literature, the accurate mechanism whereby ANGPTL8 modulates the risk and the development of dyslipidemia are needed for more investigations." (PMID 34784265, 2022). "Thus, circulating ANGPTL8 levels reflect dyslipidemia in human subjects." (PMID 29538435, 2018). "Thus, ANGPTL8 holds the potential to serve as a therapeutic target of dyslipidemia." (PMID 31741751, 2016). "ANGPTL8 is an important cytokine, which is significantly increased in type 2 DM (T2DM), obesity, and metabolic syndrome (MetS)." (PMID 40282999, 2025). "Previous studies found that circulating ANGPTL8 levels were significantly increased in metabolic disorder-related diseases, such as type 2 diabetes mellitus (T2DM), obesity, metabolic syndrome and nonalcoholic fatty liver disease (NAFLD)." (PMID 38107478, 2023). "However, the potential role of betatrophin/ANGPTL8 in septic dyslipidemia is unknown as yet." (PMID 36551906, 2022). "Inhibition of miR-143-3p significantly suppressed the ANGPTL8 expression, increased HDL-cholesterol levels, and prevented dyslipidemia and atherosclerosis progression." (PMID 33953838, 2021). "In patients with NAFLD, sleep apnea syndrome (SAS), metabolic syndrome and PCOS, circulating ANGPTL8 levels were significantly increased." (PMID 34582711, 2021). "In accordance with this, circulating ANGPTL8 levels also showed specific changes in a variety of metabolic diseases, including diabetes, obesity, non-alcoholic fatty liver disease (NAFLD), metabolic syndrome, polycystic ovary syndrome (PCOS) and so on." (PMID 34582711, 2021). "ANGPTL8 is an important cytokine, which is significantly increased in type 2 diabetes mellitus (T2DM), obesity and metabolic syndrome." (PMID 34582711, 2021). "Our earlier results have indicated that plasma ANGPTL8 level is positively correlated with BMI, SBP, HOMA-IR, and metabolic syndrome (MetS)." (PMID 30524367, 2018). "In the cohort of Beijing children and adolescents metabolic syndrome (BCAMS) study, participants with high TG (defined as ≥150 mg/dl) exhibited significantly increased ANGPTL8 concentration." (PMID 30021607, 2018). "Dyslipidemia is one of the most important factors in the pathogenesis of CAD, and ANGPTL8 plays an important role in lipid metabolism." (PMID 29940978, 2018). "Future research should investigate the feasibility of using ANGPTL3, ANGPTL4, and ANGPTL8 as biomarkers in DR and assess whether ANGPTL3-targeted therapies can improve disease progression in DR while managing dyslipidemia." (PMID 40559376, 2025).
metabolic syndrome (continued). "In addition, we also listed several novel identified modulatory biomarkers which play an important role in the regulation of dyslipidemia induced by hypothyroidism, including PCSK9, ANGPTL3, ANGPTL8, FGF-21, FGF-19, and several microRNAs." (PMID 34784265, 2022). "By contrast, in the Japanese study above, in which gender differences were not taken into consideration, obesity and dyslipidemia were positively related to circulating ANGPTL8." (PMID 34959891, 2021). "It seems that the presence of metabolic syndrome did not influence the levels of ANGPTL8; on the other hand, the presence of psoriasis slightly altered the expression of ANGPTL8." (PMID 32537470, 2020). "To date, the levels of ANGPTL8 were not measured in psoriatic patients with/without metabolic syndrome." (PMID 32537470, 2020). "In this study, we found that circulating full-length ANGPTL8 concentrations in patients with dyslipidemia were significantly elevated compared with those without dyslipidemia." (PMID 30021605, 2018). "Remarkably, circulating full-length ANGPTL8 concentrations were significantly elevated in the dyslipidemia group compared with the non-dyslipidemia group (506.18 [368.31–723.56] vs. 408.21 [294.52–511.41] pg/mL, P < 0.001)." (PMID 30021605, 2018). "In conclusion, we found that non-diabetic people with dyslipidemia had significantly increased full-length ANGPTL8 concentrations compared with those without dyslipidemia." (PMID 30021605, 2018). "Circulating ANGPTL8 concentrations were significantly elevated in patients with dyslipidemia compared with patients without dyslipidemia." (PMID 30021605, 2018). "Third, this study fails to investigate the relationships between ANGPTL8 and cardiovascular disease related biomarkers such as metabolic syndrome and inflammatory cytokines." (PMID 30007407, 2018). "Based on its function, we hypothesized that ANGPTL8 will play a role in Metabolic Syndrome (MetS)." (PMID 26850725, 2016). "We might only speculate why the level of ANGPTL8 did not increase, despite the presence of inflammation and metabolic syndrome, as we expected." (PMID 32537470, 2020). "Angiopoietin-like protein 8 (ANGPTL8) has a role in lipid metabolism, beta-cell proliferation and diabetes progression, however, the association between different variants in the ANGPTL8 gene and metabolic syndrome (MetS) components has not been studied widely especially in Arab ethnic groups." (PMID 32317770, 2020). "A study has reported that ANGPTL8 may be involved in HDL-C dysfunction, and another study has indicated the close association of ANGPTL8 with dyslipidemia regardless of glucose intolerance or diabetes mellitus." (PMID 30898163, 2019). "However, in the current study, the relationships between metabolic syndrome, inflammatory cytokines and ANGPTL8 were not assessed." (PMID 30007407, 2018). "Thus, ANGPTL8 could not be ignored as a potential object in the metabolic syndrome or endocrinology research." (PMID 35529083, 2022).
diabetes (51 papers, 2016 to 2026). "A recent study in 2025 also found a positive association between ANGPTL8 with inflammation, diabetes prevalence, and cardiovascular mortality." (PMID 40282999, 2025). "It has also been found that ANGPTL8 levels are elevated in pancreatic adenocarcinoma (PAAD)-associated diabetes patients." (PMID 38107478, 2023). "Clinical studies have associated circulating ANGPTL8 levels with metabolic diseases such as diabetes and obesity." (PMID 35529083, 2022). "Elevated levels of plasma ANGPTL8 are associated with metabolic syndrome, type 2 diabetes mellitus (T2DM), non-alcoholic fatty liver disease (NAFLD)/non-alcoholic steatohepatitis (NASH), atherosclerosis and hypertension." (PMID 34167540, 2021). "We thus attempted to clarify the circulating ANGPTL8 levels in novel subgroups of diabetes proposed by Emma Ahlqvist24 and the association of the ANGPTL8 levels with outcomes in the subsequent 5 years." (PMID 32732946, 2020). "This retrospective cohort study found that ANGPTL8 levels were elevated and independently associated with all-cause mortality and renal dysfunction in patients with diabetes." (PMID 32746907, 2020). "Future studies are needed to evaluate ANGPTL8 as a biomarker for the risk of death in cardiometabolic diseases, including diabetes and to study the underlying mechanisms for its potential role in adverse health outcomes in these diseases." (PMID 32746907, 2020). "In conclusion, this 5-year follow-up study of the REACTION study revealed that the circulating ANGPTL8 levels show differences among novel subgroups of adult patients with diabetes and are associated with all-cause mortality in the subsequent 5 years." (PMID 32732946, 2020). "Recently, associations between ANGPTL8, diabetes, and blood lipids have aroused a great deal of interest." (PMID 33343659, 2020). "This study is the first longitudinal study to detect the association between ANGPTL8 and outcomes of diabetes, particularly those in novel subgroups of diabetes." (PMID 32732946, 2020). "In conclusion, this 5-year follow-up REACTION study revealed that the circulating ANGPTL8 levels show differences among novel subgroups of adult patients with diabetes and are associated with all-cause mortality in the subsequent 5 years." (PMID 32732946, 2020). "In conclusion, serum ANGPTL8 levels were associated with an increased risk of all-cause mortality and renal dysfunction in patients with diabetes." (PMID 32746907, 2020). "Association of ANGPTL8 with diabetes and atherosclerotic diseases has been of great interest in recent studies." (PMID 29973202, 2018). "In recent studies, association of ANGPTL8 with diabetes and atherosclerotic diseases has gained much interest." (PMID 29973202, 2018). "Previous studies have suggested that serum ANGPTL8/betatrophin levels are associated with obesity and diabetes mellitus." (PMID 27345212, 2016). "Finally, we showed that the PTVs in ANGPTL4 and ANGPTL8 were associated with lower risks of diabetes-related endpoints and statin therapy respectively." (PMID 33909604, 2021). "The underlying mechanism driving the observed differences in the ANGPTL8 levels among novel diabetes groups and the association of ANGPTL8 with detrimental outcomes also remain unclear." (PMID 32732946, 2020). "ANGPTL8, an important regulator of glucose and lipid metabolism, is associated with diabetes, but the role of ANGPTL8 in the outcomes of novel subgroups of diabetes remains unclear." (PMID 32732946, 2020). "Based on these findings, the present study aimed to evaluate the levels of circulating ANGPTL8, which serves as an important factor in glucose and lipid metabolism, in subjects belonging to different novel diabetes subgroups and its association with subsequent events or complications." (PMID 32732946, 2020). "ANGPTL8 was positively associated with age, TG, diabetes duration, and c-IMT in type 2 diabetes." (PMID 30007407, 2018).
diabetes (continued). "Moreover, the presence of diabetes linked SNPs within the genes set co-expressed with ANGPTL8 was investigated." (PMID 30627105, 2018). "Moreover, the gene-SNP analysis of highly associated biological processes with ANGPTL8 revealed significant genetic signals associated to Diabetes Mellitus and similar phenotypic traits." (PMID 30627105, 2018). "Thus, it may be considered that the inference on the association of the particular variant with lipid metabolism has more impact and that the role of ANGPTL8 and the R59W variant in diabetes needs to be further clarified by more studies." (PMID 37755252, 2023). "Furthermore, inclusion of ANGPTL8 improved the performance of QFrailty scores in predicting all-cause mortality; therefore, serum ANGPTL8 levels might be used as an important biomarker for the prediction of death in patients with diabetes." (PMID 32746907, 2020). "Serum ANGPTL8 levels were associated with an increased risk of all-cause mortality and could be used as a potential biomarker for the prediction of death in patients with diabetes." (PMID 32746907, 2020). "Our aim was to investigate the association between the genetics of the angiopoietin protein-like 8 (ANGPTL8) rs2278426 (C/T) polymorphism with prediabetes (pre-DM) and type 2 diabetes (T2DM) in a Han Chinese population in Hebei Province, China." (PMID 33343659, 2020). "Background/Objectives: Angiopoietin-like proteins 4 and 8 (ANGPTL4 and ANGPTL8) are key regulators of lipid metabolism and inflammatory processes, with a potential role in the pathogenesis of type 2 diabetes mellitus (T2DM) and its complications." (PMID 42194593, 2026). "Nevertheless, the precise expression pattern of ANGPTL8 in certain pathological conditions, including obesity, diabetes, and MetS, has yet to be fully elucidated." (PMID 37767256, 2023). "In patients with type 2 diabetes mellitus, serum ANGPTL8 levels were positively correlated with the degree of inflammation and oxidative stress." (PMID 37294581, 2023). "Numerous epidemiological studies have provided evidence of the modification of ANGPTL8 levels in metabolic disorders such as diabetes, obesity, and MetS." (PMID 37767256, 2023). "ANGPTL8 is known as betatrophin, lipasin and TD26 and shows a regulatory function in lipid and glucose metabolism, which is involved in metabolic diseases such as diabetes, obesity and metabolic syndrome." (PMID 35851270, 2022). "Other experiments showed that overexpression of ANGPTL8 in db/db mice and mice with diabetes induced by high-fat diet/streptozotocin, reduces FBG levels and enhances glucose tolerance and insulin sensitivity, while ANGPTL8 knockdown has the opposite effect." (PMID 36295827, 2022). "On the other hand, the levels of ANGPTL8 in patients with diabetes were lower than NGT pregnancy women (P < 0.05)." (PMID 35529083, 2022). "Multiple regression analyses indicated that ANGPTL8 levels were important factors related to fasting hypertriglyceridemia in diabetes patients." (PMID 34293055, 2021). "The results suggest interventions targeting ANGPTL8 as new treatment options for improving lipid and glucose metabolism in diabetes patients who need enhanced treatment." (PMID 34293055, 2021). "Previous studies showed altered angiopoietin-like protein-8 (ANGPTL-8) and resistin circulating levels in type 2 diabetes mellitus (T2DM)." (PMID 34603198, 2021). "Serum levels of ANGPTL8, resistin, BMI, blood pressure, duration of diabetes, glycosylated hemoglobin (HbA1c), fasting blood glucose (FPG), hypersensitive C-reactive protein (hs-CRP), lipid profile, liver, and kidney function tests were assessed." (PMID 34603198, 2021). "We anticipate that the results of this research will facilitate potential treatments targeting ANGPTL8 in patients with diabetes." (PMID 34293055, 2021). "Previous studies suggested that serum ANGPTL8 levels increased in patients with diabetes, especially in diabetic patients with albuminuria." (PMID 34557469, 2021).
diabetes (continued). "ANGPTL8 levels were increased in diabetes, dyslipidaemia, CVD, renal function, obesity, hypertension, and nonalcoholic fatty liver." (PMID 32746907, 2020). "In this population-based longitudinal study of novel clusters of diabetes, we found that ANGPTL8 was significantly elevated in the MARD, SIRD, and SIDD clusters compared with the MOD cluster." (PMID 32732946, 2020). "Several studies have shown that ANGPTL8 in circulating blood is elevated in patients with diabetes and obesity." (PMID 33343659, 2020). "Increased insulin levels in patients with diabetes, as shown in our study, are among the important factors for stimulating ANGPTL8 production." (PMID 32746907, 2020). "It is reported that ANGPTL8 concentrations were further reduced up to 70% in obese participants with diabetes." (PMID 32440963, 2020). "Angiopoietin-like protein 8 (ANGPTL8) is an adipokine and circulating ANGPTL8 is related to metabolic and inflammatory parameters, and oxidative stress, in patients with type 2 diabetes mellitus." (PMID 32034642, 2020). "According to ROC curve analysis, the inclusion of ANGPTL8 in QFrailty score significantly improved its predictive performance for mortality in patients with diabetes." (PMID 32746907, 2020). "Another evidence linking ANGPTL8 with CMS is a paper investigating the ANGPTL8 in 556 diabetes with T2D and showing that ANGPTL8 level was three times higher in diabetic patients with T2D compared to controls." (PMID 32456228, 2020). "Patients with diabetes and CAD have remarkably higher levels of ANGPTL8 than those with only diabetes." (PMID 29940978, 2018). "Serum ANGPTL8 levels positively correlated with duration of diabetes in all type 2 diabetic groups (all P < 0.05)." (PMID 30072957, 2018). "Results on the comparison of ANGPTL8 concentration between controls and diabetes were inconsistent; presenting increased, decreased, or unchanged." (PMID 29719529, 2018). "ANGPTL8 levels were positively correlated with triglycerides, duration of diabetes, and urine albumin-to-creatinine ratio (ACR) and negatively correlated with estimated glomerular filtration rate in type 2 diabetic patients with A2 and A3 (all P < 0.05)." (PMID 30072957, 2018). "Here, we report that adenovirus-mediated expression of mouse ANGPTL8 over 2 weeks alters glucose homeostasis and lipid profiles in 3 mouse models of diabetes." (PMID 31741751, 2016). "Nevertheless, the relationship between circulating levels of ANGPTL8 and diabetes and obesity remains inconclusive." (PMID 27053679, 2016). "While several global genome-wide association studies exist relating the ANGPTL8 R59W variant with lipid traits, only a couple of studies exist relating ANGPTL8 (and not the R59W particularly) with diabetes." (PMID 37755252, 2023). "Another study has demonstrated that individuals with impaired glucose tolerance and type 2 diabetes mellitus exhibit notably heightened serum levels of ANGPTL8, suggesting that ANGPTL8 may play a role in the onset of this disease." (PMID 36983346, 2023). "Furthermore, the prevalence of hypertension, hyperlipidaemia and diabetes increased in the highest quartile of ANGPTL8 levels (p < 0.05)." (PMID 34167540, 2021). "However, some clinical reports have demonstrated that circulating ANGPTL8 levels in type 2 diabetes patients are elevated compared with those in non-diabetes individuals; ANGPTL8 levels are also elevated in obese individuals." (PMID 34293055, 2021). "This study aimed to investigate circulating levels of ANGPTL8 in participants with and without diabetes and its potential associations with clinical outcomes in a 5 year cohort study." (PMID 32746907, 2020). "In this work, we retrospectively investigated circulating levels of ANGPTL8 in participants with and without diabetes and its potential associations with death and cardiovascular and renal outcomes in a 5 year cohort study." (PMID 32746907, 2020). "First, we found that ANGPTL8 was relatively low in the novel MOD cluster of diabetes." (PMID 32732946, 2020).